MIR617 (microRNA 617)
Synonyms: hsa-mir-617; MIRN617
Gene: MicroRNA gene on chromosome 12 (80,832,533 to 80,832,629, reverse strand). Ensembl gene ENSG00000207763.
Homologues: Orthologues: chimpanzee ptr-mir-617 (100% identical).